FGFR3 (fibroblast growth factor receptor 3)
Diseases named in the same sentence as FGFR3 in open-access papers (continued):
Sharing a sentence is not in itself a finding about the gene and the disease.
tumor (continued). "We aimed to assess whether FGFR3 could function as an oncogene and promote tumor malignancy." (PMID 27829236, 2016). "As expected, FGFR3 immunohistochemical scores were significantly associated with FGFR3 mutations (ANOVA P = 3×10−5, KW P = 3×10−4) and were higher in the low grade NMIBC than in the more aggressive tumor groups of high grade NMIBC and MIBC (ANOVA P = 0.038, KW P = 0.026)." (PMID 23650517, 2013). "For this analysis, among the 6 groups constituted for this study, we worked with the two homogenous tumor groups with the higher number of samples: the Ta G1/G2 (FGFR3-mutated) tumor group (28 samples) and the stage T2–4 (FGFR3-non-mutated) tumor group (63 samples)." (PMID 22724020, 2012). "Interestingly, more genes were found to be up-regulated in the FGFR3-non-mutated tumor pathway (12 genes) as compared to the FGFR3-mutated tumor pathway (4 genes)." (PMID 22724020, 2012). "Most of the deregulated genes in the FGFR3-non-mutated tumor pathway were found in this group." (PMID 22724020, 2012). "Consequently, a switch to IIIc as the main FGFR3 isoform may permit stimulation of tumour cells by those additional factors." (PMID 20234367, 2010). "In addition, 3 out of 3 of 1000 cells prepared from FGFR3+ tumour inoculated mice formed tumour." (PMID 19888223, 2009). "In addition, tumours formed by FGFR3-positive cells could be used for serial propagation of tumours in animals." (PMID 19888223, 2009). "In addition, xenoengraftment of 33% of single FGFR3-positive KYM-1 cells yielded tumour formation." (PMID 19888223, 2009). "IHC revealed that LZU‐WZLYCS01 treatment markedly downregulated the expression of FGFR3, MAD2L1, and Ki‐67 in tumor tissues." (PMID 41168906, 2026). "Most reports describe FGFR3::TACC3 as an acquired event after EGFR-TKI therapy, and its presence in a TKI-naïve tumor suggests a potential de novo co-activation of independent oncogenic pathways." (PMID 41301039, 2025). "FGFR3 stimulates Stearoyl-CoA Desaturase 1 (SCD1) activity and thus promotes tumour growth in bladder tumour cells." (PMID 41008920, 2025). "Compared to the vehicle control, SLC7A7 knockdown significantly delayed tumor volume and weight and increased the expression of miR-152-3p, which consequently resulted in a decrease in CD32 and FGFR3 levels." (PMID 40075158, 2025). "Treatment with derazantinib and GEM synergistically inhibited the malignant behaviors of GEM-resistant PDAC cells and tumor growth by downregulating FGFR2 and FGFR3 expression." (PMID 41467942, 2025). "Current treatments utilize FGFR3 inhibitors to mitigate aberrant activation of the MAPK-ERK and JAK-STAT pathways, thereby enhancing anti-tumor effects." (PMID 40943615, 2025). "Our animal experiments revealed that talazoparib induced FGFR3 phosphorylation, and that PD173074 dose-dependently inhibited talazoparib-induced FGFR phosphorylation in tumor tissues harvested 3 days after treatment." (PMID 40460005, 2025). "Research demonstrates that FGFR expression remains more stable in highly aggressive tumors, and FGFR3 overexpression or aberrant activation of other FGFR family members (e.g., FGFR1) can promote tumor progression and metastasis via ligand-dependent mechanisms." (PMID 41438986, 2025). "This study showed a notably high diversity of FGFR3::TACC3 rearrangements in UCs, as was also shown previously for other tumor types." (PMID 39596194, 2024).
tumor (continued). "Conventional FGF1 and unconventional FGF2 interact with FGFR3 and FGFR1 on tumours, respectively, which promotes the enhancement of tumour cell invasion mediated by CAFs." (PMID 40135140, 2024). "Downregulation of hsa-miR-99a, as shown in our study, leads to abnormal expression of the FGFR3 gene, resulting in the activation of PI3K-AKT and RAS/RAF/MEK/MAPK signaling pathways involved in tumor progression." (PMID 39595529, 2024). "Hub genes with high centrality, including PTK6, FGFR3, and FGFR4, which have been recognized as therapeutic targets in tumor treatment." (PMID 38347596, 2024). "Lenvatinib prevents tumor angiogenesis through inhibition of VEGFR-1, -2, and -3, and also blocks the proliferation of tumor cells through inhibition of FGFR-1, FGFR-2, FGFR-3, & FGFR-4, PDGFRα, RET, and c-KIT." (PMID 38622735, 2024). "By inhibiting FGFR3, anlotinib blocks downstream signaling pathways, such as the RAS/RAF/MEK/ERK and PI3K/AKT pathways, which are crucial for tumor growth and survival." (PMID 39421453, 2024). "sGAG‐mimetic alginate sulfate leads to activation of a specific set of RTKs (FGFR3 and RYK) in tumor cells and the downstream FAK‐PI3K signaling axis." (PMID 39083319, 2024). "This case-control study was conducted between 2020 and 2023, in which n = 115 tumor tissues (NMIBC n = 85) and (controls n = 30) were examined for FGFR3 and FGFR promoter methylation and expression using methylation-specific PCR (MSP) and real-time PCR." (PMID 39219882, 2024). "Fibroblast growth factor receptors (FGFRs) comprising FGFR1,FGFR2,FGFR3 and FGFR4 have been reported to play important roles in the regulation of the main target genes of lenvatinib and control tumour metabolism in many cancer types including HCC." (PMID 37846441, 2023). "Among the FGFR family members (FGFR1, FGFR2, FGFR3, and FGFR4), only FGFR2 was significantly upregulated in PanCK(+) tumor epithelial cells at the EOCC tumor invasive margin compared to the LOCC tumor invasive margin in NGDSP analysis." (PMID 37964075, 2023). "This further reduces Treg differentiation and PD-L1 content in the tumor, thereby reducing TGF-ß signaling and FGFR3 inhibition for improving the anti-PD-1 therapeutic effect." (PMID 36875116, 2023). "Another study showed that either Fgfr1, Fgfr2, or Fgfr3 gene knockout impeded SS18-SSX2-induced tumour formation in vivo and FGFR inhibitor (BGJ398) treatment reduced SS tumour cell growth in vitro and in vivo." (PMID 37130917, 2023). "It is established that the IgLON family member OPCML acts as a tumor suppressor by eliciting the downregulation or the inhibition of RTKs, such as EphA2, FGFR1, FGFR3, HER2, HER4, and AXL." (PMID 37765276, 2023). "Notably, FGFR3 alterations were frequently correlated with the non-T cell inflamed tumor microenvironment which was associated with resistance to immunotherapy, besides, frequently altered FGFR3 was found to be enriched in the luminal UC subtype poorly responding to immunotherapy." (PMID 36818471, 2022). "To verify the relationship between METTL3, FGFR3 and antitumor sensitivity of anlotinib in vivo, we explored the expression level of METTL3 and FGFR3 of tumor tissues from eight previously established OSCC PDX models." (PMID 36167542, 2022). "Two patients with FGFR3-amplified Sq-NSCLC have been reported: one with tumor shrinkage by 25% and the other (with concomitant FGFR1 amplification) with a 10% increase in tumor size." (PMID 35402233, 2022).
tumor (continued). "The expression of FGFR3 and FGFR4 were significantly higher in tumor than in normal samples in GC (p<0.001)." (PMID 36147913, 2022). "Consistently, FGF18 expression and secretion are upregulated in a high-RPS15 A-expression HCC tumor microenvironment; FGF18 interacts with FGFR3 and contributes to angiogenesis by inducing the Wnt/β-catenin signaling pathway in endothelial cells." (PMID 33935756, 2021). "Another study showed that in HNSCC cells, co-inhibition of MEK and FGFR3 activity reduced AKT and ERKs phosphorylation, which in turn led to increased DNA fragmentation, caspase 3 cleavage, and reduced tumor growth in vivo." (PMID 34830951, 2021). "Importantly, we observed that wild-type FGFR3 tumours in the UROMOL validation cohort were significantly associated with a higher RNA-derived immune infiltration score (n = 129; Wilcoxon rank sum test, p = 0.003), indicating a tumour microenvironment with an immune system supportive of response." (PMID 34934968, 2021). "TAMs, which promote tumour cell viability, secrete FGF, which binds with FGFR3 and supports CAF survival and activation." (PMID 34059019, 2021). "The treated tumor showed several CNVs in driver genes, including amplifications in MCL1, TERT, CCND1, AKT1, MYC, EGFR, and FGFR3; deletions in CDK1B, CDKN2A and CDKN2B; a PIK3CA hotspot mutation; and a high TMB." (PMID 34680239, 2021). "Thus, we did not expect the FGFR3 activating mutation to have a significant impact on tumor growth." (PMID 34984415, 2021). "BGJ398 also showed strong antitumor activity in an HCC patient-derived tumor xenograft (PDX) model expressing high FGFR2 and FGFR3 with acquired sorafenib resistance." (PMID 33802841, 2021). "Presumably, FGFR3 kinase plays a key role in regulating infected epithelium cells by limiting HPV replication, inhibiting tumorigenesis, and tumor growth." (PMID 34925445, 2021). "Both FGFR3 and eIF4E have previously been shown to be overexpressed in several types of cancers, including CRC, and they have both also been found to promote tumor growth." (PMID 32731506, 2020). "Results showed that gene signatures such as PSMA1, FGFR3, C7orf46, RNF7, and ZNF35 were differentially expressed in normal and tumor samples with the P-value < 0.05." (PMID 32528533, 2020). "Therefore other molecular changes may drive an upregulation of ETV5 in FGFR3-wild type tumours." (PMID 30952872, 2019). "A previous study showed that silencing FGFR1 expression using small interfering RNA was effective in elevating FGFR3 expression and tumor supportive activity, suggesting that FGFR1 and FGFR3 have an inverse relationship." (PMID 31369573, 2019). "The expression of FGFR3, PLCB4, and IKBKB were downregulated in the tumor tissues as compared to the adjacent normal tissues." (PMID 31729423, 2019). "Forty-four unique fusions were identified in 40 (1.1%) of the 3,808 patients with circulating tumor DNA detected: RET (n = 6; 36% of all fusions detected), FGFR3 (n = 2; 27%), ALK (n = 10, 23%), NTRK1 (n = 3; 7%), ROS1 (n = 2; 5%), and FGFR2 (n = 1; 2%)." (PMID 33015522, 2019). "The recurrent tumour showed a 70–80 fold increase of expression of transcription factors ASCL1 and HOXA1 and tyrosine kinases FGFR3, HER3, HER4 and MET." (PMID 31747973, 2019). "The FGFR3-BAIAP2L1 fusion promotes ligand-independent phosphorylation of FGFR3-BAIAP2L1 in Rat-2_F3-B cells and tumor formation in nude mice inoculated with Rat-2_F3-B cells by activating ERK and STAT1 signaling, similar to FGFR2-CCDC6." (PMID 31007851, 2019). "These pathways were all connected to tumor growth, and the PI3K/Akt signaling pathway (eight involved genes: CCND2, CDKN1B, CSF1, EFNA3, FGFR2, FGFR3, IL2RB, and ITGA9) ranked first among upregulated pathways (Enrichment Score = 3.159187)." (PMID 30755239, 2019). "No remarkable correlations nonetheless were discovered between FGFR3 and age, gender, TNM stage, tumor size, or distant metastasis." (PMID 29850625, 2018).
tumor (continued). "As in cell lines, FGFR3‐S249C expression conferred FGFR3 dependence on the PDX model, in which anti‐FGFR treatment with BGJ398 decreased tumor growth by 60% after 29 days of administration." (PMID 29463565, 2018). "Some of these amplified genes are well-known tumor related genes, such as AKT2, FGFR3, FGF10, SDHA, CCNE1, PI3KCA, and etc." (PMID 28029662, 2017). "Like FGFR3, FGF9 expression has also been identified in several tumor types, including breast, prostate, endometrioid and lung, suggesting an important role in tumorigenesis." (PMID 27056048, 2016). "Exploratory molecular analysis of the patient’s archival tumour sample included FGFR1 and FGFR3 protein expression by immunohistochemistry (IHC) and next-generation sequencing (NGS) analysis at Foundation Medicine." (PMID 26497743, 2015). "The comparison of the genetic characteristics of muscle-invasive and non-invasive tumours revealed that non-invasive tumours over-express HRAS and FGFR3 or produce highly activated forms of these proteins." (PMID 25569276, 2015). "All genes were significantly down-regulated in 2D culture relative to the parental tumor, with the most differentially expressed markers including CD105, NRP1, FGFR3 and MMP2 (p < 0.005)." (PMID 26203665, 2015). "Four tumours could not be analysed in FGFR3 mutation analysis." (PMID 24650297, 2014). "A high-level CCND3 tumor (Case OC-07) showed co-amplification of MYC and AKT2; and a high-level MYC tumor (OC-08) was co-amplified for JAK2, FGFR3, and MYB." (PMID 23289505, 2013). "Based on current knowledge on the mutation load of human tumors, it is likely that yet unidentified oncogenes - different from FGFR3, PIK3CA, and RAS - and tumor suppressors participate in UBC." (PMID 23650517, 2013). "As FGFR3 and FGFR1 are altered in the majority of superficial tumours and in a good proportion of invasive tumours, they represent very inviting therapeutic targets." (PMID 22899908, 2012). "Overexpression of FGFR3 would be particularly deleterious if accompanied by a switch to alternative isoforms with different FGF affinity profiles, which would allow tumour cells to activate FGF signalling in response to a greater number of substrates." (PMID 22899908, 2012). "Of note, we also found increased expression of FGFR3, coding for a high-affinity FGF9 receptor, in 3 primary tumor profiles and several metastases." (PMID 21853123, 2011). "Several genes, such as TMPRSS4, STAR, ST7L, HAS3, FGFR3, CASZ1 and HR, were found to have gene expression changes at the very earliest stages of tumor thickening." (PMID 18442402, 2008). "Neither the anti‐FGFR3 antibody (5 mg kg−1) nor A2 (0.1 mg kg−1) exhibited significant tumor growth inhibition, and gemcitabine (20 mg kg−1) combined with cisplatin (2 mg kg−1) showed moderate therapeutic effects." (PMID 41168906, 2026). "This fusion involves fibroblast growth factor receptor 3 (FGFR3) and transforming acidic coiled-coil containing protein 3 (TACC3), leading to the constitutive activation of oncogenic signaling pathways that promote tumor growth and progression." (PMID 40417325, 2025). "These three tumors are suggestive of a potential tumor entity driven by the FGFR3::TACC3 fusion and lacking HPV infection, which merits further delineation in the future when more cases are reported." (PMID 39387893, 2025).
tumor (continued). "This case highlights the potential radiological characteristics of diffuse gliomas with FGFR3::TACC3 fusion, particularly the presence of coarse calcifications, that may serve as notable imaging features of this tumor." (PMID 40417325, 2025). "While considering tumour stage, 95% of NMIBC showed a strong pattern of FGFR3 staining." (PMID 41375830, 2025). "FGFR3 was positive in the molecular layer of the cerebellar cortex and tumor cells, while FGFR2 was positive in tumor cells, glial cells, and blood vessels, and FGFR4 was positive in tumor cells, astrocytes, and blood vessels." (PMID 40393028, 2025). "Additionally, cyclin D1 (CCND1; chr 11q), fibroblast growth factor receptor 3 (FGFR3; chr 4p), and PIK3CA (chr 3q) were amplified in the tumor tissues from patients S390 and S425, S425 and S028, and S425 and S424, respectively." (PMID 41301905, 2025). "We identified highly expressed genes in each cluster, and FGFR3 was found in both the radial glial/astrocyte-like and tumor cell clusters but not in the neuron cell cluster." (PMID 38609519, 2024). "Furthermore, studies have reported that FGFR3 and MYC overexpression led to an increase in Tregs, inducing an immunosuppressive tumor microenvironment (TME), while ERBB2 overexpression was linked to a decrease in Tregs." (PMID 39410541, 2024). "Our scRNA-seq profiling of control or erdafitinib-treated UPFL tumors demonstrates that oncogenic FGFR3 alterations drive a luminal phenotype in all urothelial tumor cell types, suggesting that FGFR inhibition may impact a broad range of tumor cell types." (PMID 38226620, 2024). "Although FGFR3 and its related PI3K-AKT transduction are activated in tumor models, we speculate that the function of PI3K-AKT pathway in chondrocyte is different due its multiple biology." (PMID 37640697, 2023). "Interestingly, there was visually apparent co-localization of tumor neuroectoderm-like cells with high PTPRZ1, PTN, and FGFR3, identified as important for neuroectoderm-like neoplastic cell signaling as above." (PMID 36966348, 2023). "Moreover, NF-CM, TAF-CM, and FGF (ligand for FGFR3) were applied on FGFR3 knocked-down PA cells, and we observed that TAF-CM as well as FGF induced tumor growth can be notably attenuated by FGFR3 knockdown." (PMID 37444485, 2023). "FGFR3 immunostaining allows the highlight of tumor cells, as the normal brain does not stain for FGFR3 (with the exception of the cerebellar and cerebral molecular layers, which weakly express FGFR3)." (PMID 38067258, 2023). "In addition, we found that FGFR2, FGFR3 and FGFR4 expression was increased in the tumour tissues compared to that in normal tissues in the TCGA_LIHC datasets." (PMID 37846441, 2023). "In addition, the FGFR3 splice isoform, FGFR3 IIIb/IIIc, and its ligand, FGF9, have been found to be upregulated in HCC, promoting tumor cell growth and aggressiveness." (PMID 37750089, 2023). "The analysis revealed high correlation within FGFR1, FGFR2, and FGFR3 expression assessed with both methods (r = 0.77, p = 0.000001; r = 0.86, p = 0.000001; and r = 0.95, p = 0.000001, respectively) in 40 Sq-NSCLC tumor samples." (PMID 36142417, 2022). "FGFR2 and FGFR3 mRNA expression varied between tumor and tumor-adjacent normal tissues and were enhanced 2–10 times in several tumor samples." (PMID 36142417, 2022). "However, in individual tumor samples, FGFR2 and FGFR3 expression levels were enhanced: fold-changes > 2 were observed in 5 (12.5%) and 7 (17.5%) samples, respectively." (PMID 36142417, 2022).